OR10H1 (olfactory receptor family 10 subfamily H member 1)
Description:
Odorant receptor.
Tractability: Antibody: UniProt places it where antibodies can reach, with medium confidence; UniProt predicts a signal peptide or a membrane-spanning region; its Gene Ontology location is reachable by antibodies, with medium confidence.
Gene: Protein-coding gene on chromosome 19 (15,804,549 to 15,815,664, reverse strand). Ensembl gene ENSG00000186723.
Subcellular location: Cell membrane
Pathways (Reactome):
Sensory Perception: Expression and translocation of olfactory receptors
Gene Ontology:
Molecular function: olfactory receptor activity; G protein-coupled receptor activity
Biological process: detection of chemical stimulus involved in sensory perception of smell; G protein-coupled receptor signaling pathway
Cellular component: plasma membrane; membrane
Genetic constraint (gnomAD): Loss-of-function variants: 12 observed, 13 expected, observed/expected ratio (o/e) 0.92, 90% interval 0.59 to 1.49. The upper end of that interval is the gene's LOEUF score, 1.49, which puts it in group 6 of 6, group 1 being the genes least tolerant of losing a copy. Missense variants: 357 observed, 401.24 expected, observed/expected ratio (o/e) 0.89, 90% interval 0.81 to 0.97. Synonymous variants: 167 observed, 169.54 expected, observed/expected ratio (o/e) 0.99, 90% interval 0.87 to 1.12.
Homologues: Orthologues: macaque OR10H5 (90% identical), mouse Or10h1 (85% identical), rat Or10h1 (85% identical), rat Or10h1d (85% identical), mouse Or10h1b (84% identical), rat Olr1090 (83% identical), mouse Or10h5 (83% identical), rat Olr1092 (82% identical), rat Olr1093 (82% identical). Paralogues in human: OR10H5 (92% identical), OR10H2 (87% identical), OR2K2 (47% identical), OR10A5 (47% identical), OR10A2 (45% identical), OR10C1 (45% identical), OR10A3 (45% identical), OR13D1 (45% identical), OR10A7 (44% identical), OR10AG1 (44% identical), OR10A6 (43% identical), OR13C4 (43% identical), and 80 more.
Diseases named in the same sentence as OR10H1 in open-access papers:
OR10H1 is named in the same sentence as 6 diseases in open-access papers, as found by Europe PMC text mining. Sharing a sentence is not in itself a finding about the gene and the disease. The quoted sentences say what the papers report.
bladder cancer (8 papers, 2018 to 2024). "OR10H1 is predominantly expressed in the testis and urinary bladder and was shown to be highly expressed in bladder cancer cell lines." (PMID 33717105, 2021). "Researchers from Bochum detected OR10H1 in the human urinary bladder with notably higher expression at mRNA and protein levels in bladder cancer tissues." (PMID 33566867, 2021). "OR10H1 is predominantly expressed in the urinary bladder, among all tissues, with increased expression in many bladder cancer tissues." (PMID 29867524, 2018). "OR10H1 was expressed in 23 out of 25 bladder cancer tissue samples, with an average FPKM-value of 3.8, whereas it was only moderately expressed in the normal bladder (n = 5) with an average value of 0.3." (PMID 29867524, 2018). "Validation of OR10H1 protein expression was performed via immunohistochemical staining with a specific OR10H1-detecting antibody in bladder cancer tissues." (PMID 29867524, 2018). "In the present study, we describe a specific GPCR, OR10H1, belonging to the class of ORs, which is highly specific for the urinary bladder, but moreover has a significantly higher expression in bladder cancer tissues." (PMID 29867524, 2018). "In this study, we describe that one OR, OR10H1, is predominantly expressed in the human urinary bladder with a notably higher expression at mRNA and protein level in bladder cancer tissues." (PMID 29867524, 2018). "Transcripts of OR10H1 are detectable at significantly higher levels in the urine of bladder cancer patients." (PMID 29867524, 2018). "Urine samples from patients with bladder cancer revealed a significantly higher amount of OR10H1 transcripts than urine samples from healthy donors." (PMID 29867524, 2018). "Further studies should address the relationship between OR10H1 expression and the recently defined molecular subtypes of bladder cancer to evaluate its potential usefulness as a biomarker for a defined subset of bladder cancer tissues." (PMID 29867524, 2018). "There is also one report that the closely related receptor OR51E1 also inhibits growth of prostate cancer cells and another that OR10H1 plays a potential role in bladder cancer." (PMID 30542293, 2018). "This deorphanization allowed the functional characterization of OR10H1 in BFTC905 bladder cancer cells." (PMID 29867524, 2018). "Beside the identification of OR10H1 as a potential biomarker, we aimed to characterize its influence on bladder cancer cells." (PMID 29867524, 2018). "Finally, we are aware of one study which reported expression of an OR in human bladder (with upregulated expression in bladder cancer): OR10H1." (PMID 33932109, 2021). "Next, we investigated whether OR10H1 mRNA can be detected in urine from healthy human donors and patients with bladder cancer." (PMID 29867524, 2018). "Thus, OR10H1 showed a specific expression in bladder urothelium with a higher expression in many bladder cancer tissues than in normal tissue." (PMID 29867524, 2018). "Based on the fact that modulation of cytokines is important in cancer therapy, especially in the metaphylaxis of early stage bladder cancer, we investigated the effect of OR10H1 activation on the synthesis of cytokines, which revealed a significant increase in IL10 and IL15 upon stimulation." (PMID 29867524, 2018). "Interestingly, also significantly higher amounts of OR10H1 transcripts were detectable in the urine of bladder cancer patients than in the urine of control persons." (PMID 29867524, 2018). "Our results suggest OR10H1 as a potential biomarker and therapeutic target for bladder cancer." (PMID 29867524, 2018). "Strikingly, we detected transcripts of OR10H1 not only in the bladder cancer tissues but also in the urine of bladder cancer patients, and again, there were significantly higher amounts in the urine of bladder cancer patients compared to the healthy test persons." (PMID 29867524, 2018). "In the present study, we describe expression of the OR OR10H1 in bladder cancer." (PMID 29867524, 2018).
bladder cancer (continued). "In addition, OR10H1 gene expression is significantly higher in bladder cancer tissues than in normal bladder tissue, and the stimulation of this receptor by its ligand suppresses bladder cancer progression." (PMID 33802009, 2021). "This suggests that OR10H1 might be a potential biomarker that is specific for bladder cancer." (PMID 29867524, 2018).
tumor (2 papers, 2018 to 2020). "Our findings suggest that further studies should address the usefulness of OR10H1 as a potential tumor biomarker and target for therapy, to be used as a supportive approach in normal and cancerous urinary bladder tissues." (PMID 29867524, 2018).
OR10H1 also shares sentences with these, for which no sentence is quoted: cancer (3 papers); infection (1); neurodegenerative disease (1); Parkinson disease (1).